INS (insulin)
Diseases named in the same sentence as INS in open-access papers (continued):
Sharing a sentence is not in itself a finding about the gene and the disease.
Insulin resistance (continued). "Later in gestation, when insulin resistance is more pronounced and antidiabetic treatment may be intensified with diet and sometimes insulin, the rate of protein turnover is increased in women with insulin treated GDM." (PMID 33036170, 2020). "Moreover, the upregulation of SIRT1 by RSV results also in the repression of NF-κB pro-inflammatory responses in adipocytes and macrophages that infiltrate adipose tissue, leading to an improvement in insulin signaling and insulin resistance, as it was shown in genetically obese db/db mice." (PMID 32872317, 2020). "Adiponectin can improve insulin resistance induced by a high-fat diet, suggesting that adiponectin may have an insulin-sensitizing effect that may be achieved by activating the AMP-activated protein kinase signaling pathway to promote glucose and fatty acid utilization." (PMID 33324342, 2020). "Furthermore, as CAPE is also able to reduce insulin resistance, it can be argued that this blood pressure-lowering effect might also be attributed to increased vasculature sensitivity to insulin’s vasorelaxant action." (PMID 33343392, 2020). "Thus, we asked whether our protocol of chronic insulin exposure could have induced insulin resistance by evaluating the insulin signalling pathway after acute insulin stimulation." (PMID 32718202, 2020). "However, it has previously been postulated that there are acute and chronic effects of PA on insulin resistance, which may account for improvements in insulin action and decreased blood glucose levels as a response to engagement in PA." (PMID 32429951, 2020). "Since the insulin/insulin-like growth factor axis simulates the proliferation of thyroid follicular cells, it was hypothesized that compensatory hyperinsulinemia following insulin resistance in previous MetS might be responsible for the rising trend of TNs." (PMID 32973687, 2020). "When people were infected by SARS-COV-2, the decrease of insulin secretion and the worsening of insulin resistance may induce hyperglycemia, with immunoreaction and inflammatory activation, which, in turn, may further damage β-cells and worsen insulin resistance." (PMID 33062712, 2020). "In addition to insulin resistance, inflammatory cytokines induce macrophage infiltration and the apoptosis of β-cells from pancreatic islets, which compromise the pancreatic production of the higher insulin amounts required by insulin-resistant individuals." (PMID 32604771, 2020). "First, although low serum amylases may be caused by insulin resistance and reduced insulin secretion, insulin levels were not measured in this study, and therefore, precise underlying mechanism remains to be elucidated." (PMID 32375859, 2020). "In a HFD‐induced model of obesity and insulin resistance, we found that treatment with the Krebs cycle intermediate succinic acid seems to decrease white adipose tissue mass, though did not impact caloric intake, body mass, physical activity, or glucose/insulin tolerance." (PMID 33185326, 2020). "Deficiency of PKBα/β caused insulin resistance in mouse heart, and the abundance of their substrates including AS160, RalGAPα1, RalGAPα2, and TSC2 in the PAS immunoprecipitates was substantially lower for PKBα/β-deficient mouse heart relative to wild-type mouse heart upon insulin stimulation." (PMID 32367034, 2020). "T2D is described by a double defect: insulin is not sufficiently produced to meet the body’s needs, leading to a deficit of insulin secretion, or, the insulin produced does not work adequately thus causing the well-known insulin resistance." (PMID 33467298, 2020). "Given that hepatic steatosis, glucose intolerance and insulin resistance are common complications during obesity and that our data indicate that PSOn treatment effectively improved glucose and insulin levels in HFD-fed mice, we decided to evaluate if the hepatic steatosis could also be improved." (PMID 32943651, 2020).
Insulin resistance (continued). "However, an imbalance of the p85α/p110β ratio could cause either increased or decreased PI3K activity, which could impair insulin signalling and produce insulin resistance." (PMID 31936857, 2020). "In humans, myo-Ins has been shown to potentially reduce the symptoms of metabolic syndrome, including insulin resistance and dyslipidemia, as well as affect other endocrine disorders such as polycystic ovary syndrome, all of which relate to its role as an insulin mimetic." (PMID 32676038, 2020). "In skeletal muscle of mice with obesity and T2DM, disrupted ER–mitochondria contacts were shown to be an early event preceding mitochondrial dysfunction and insulin resistance, indicating that the disruption of ER–mitochondria coupling may contribute to muscle insulin resistance." (PMID 33329397, 2020). "Uric acid may adversely affect the insulin signalling pathway inducing insulin resistance (IR)." (PMID 32825165, 2020). "Moreover, UA may directly affect the intracellular insulin signalling pathway, consequently inducing insulin resistance (IR)." (PMID 32825165, 2020). "Furthermore, insulin resistance may also contribute to cognitive deficits in AD, seeing that healthy brain insulin signaling has been found to be crucial for learning and memory." (PMID 32075060, 2020). "The liver of a diabetic patient is a major site of insulin resistance that manifests itself by an overproduction of glucose during the basal state, despite fasting hyperinsulinemia and hyperglycemia and impaired suppression of hepatic glucose production in response to postprandial insulin secretion." (PMID 33379327, 2020). "Lopez-Rios et al18 reported an increased levels of insulin and HOMA in individual homozygotes for the B1 allele rather than subjects carrying at least one B2 allele that may suggest the effect of the TaqIB polymorphism on parameters of insulin resistance." (PMID 33123324, 2020). "Additionally, the sister’s postprandial insulin was elevated (414.9-438μIU/mL), fitting the hypothesis that she has early signs of the severe insulin resistance phenotype." (PMID 33210059, 2020). "In addition, miR-29 family has important roles in insulin secretion and insulin resistance." (PMID 33195407, 2020). "Taken together, and opposing previously established diabetogenic features of insulin resistance, incomplete impairment of insulin signaling may mimic central aspects of calorie restriction to limit hepatic lipid accumulation during conditions of metabolic stress." (PMID 32350271, 2020). "Indeed, genetic deletion of CB1R in hepatocytes partially protects mice from developing DIO-related hepatic steatosis, hyperglycemia, dyslipidemia, and insulin resistance, whereas its overexpression in hepatocytes contributes to insulin resistance via inhibition of insulin signaling and clearance." (PMID 33210603, 2020). "However, insulin resistance is also related to dysfunction in a broader, integrated network of metabolic hormones beyond insulin, including peptide tyrosine tyrosine (PYY), glucagon like peptide-1 (GLP-1), and glucose-dependent insulinotropic polypeptide (GIP)." (PMID 33328877, 2020). "Thus, genes on Chr 11 under high sucrose environment contributed to either phenotype acceleration (early development and marked degree of hyperglycemia, impaired insulin secretion, and insulin resistance) or new phenotype development (obesity, adiposity, and fatty liver)." (PMID 32703163, 2020). "Thus, impaired insulin secretion as well as increased insulin resistance could affect glucose intolerance in patients with phaeochromocytoma." (PMID 33324347, 2020). "However, it has remained unclear whether the main factor of glucose intolerance is impaired insulin secretion or increased insulin resistance." (PMID 33324347, 2020).
Insulin resistance (continued). "By using 3.16 as a cut off for HOMA-IR, about 40% of obese children showed impaired insulin sensitivity, presumably attributed to obesity as prepubertal children were selected in order to rule out as much as possible the confounding effect of puberty in insulin resistance." (PMID 32664439, 2020). "Since skeletal muscle is the major targets of insulin action and the key determinant of the resting metabolic rate, thus modulation of the mitochondrial function/efficiency in this tissue has been suggested as a potential approach to treat obesity and insulin resistance." (PMID 32235294, 2020). "Also, it had effects on insulin resistance and insulin secretion." (PMID 32684830, 2020). "Obesity and insulin resistance are also important risk factors for the development of endometrial cancer where knockdown of YAP/TAZ has been shown to inhibit insulin signalling via phosphorylation of IRS1/2, a mediator of insulin and IGF-1 signalling in endometrial cell lines." (PMID 31936297, 2020). "Therefore, a decrease of CNS sensitivity to insulin has been proposed as the potential link between metabolic and cognitive dysfunctions, and the multiple roles of insulin in the brain, as well as the effects of brain insulin resistance, have been extensively reviewed by Kullman." (PMID 33374894, 2020). "With T2DM progressing over time, by increasing insulin resistance and impaired beta-cell function, the need of antidiabetic drugs to maintain glycemic control increases, and eventually, the beta-cell function is impaired to an extent where exogenous insulin is needed." (PMID 32903679, 2020). "Insulin resistance is generally associated with overweight and obesity, but without having insulin glucose clamp studies at this point, we could not definitively conclude that the participants in our study are insulin resistant." (PMID 32823525, 2020). "It highlighted that UAG might improve insulin sensitivity while AG induces insulin resistance." (PMID 32963741, 2020). "Insulin resistance is critically dependent on liver inflammation with studies showing that constitutively active hepatic nuclear factor-kappaB (NF-κB), the central mediator driving the inflammatory response, leads to an insulin resistant state in a mouse model." (PMID 31914125, 2020). "Studies show that HFD-induced insulin resistance alters dopamine terminal function in the NAc, which is reversed by restoring insulin signaling, suggesting central insulin resistance after HFD exposure may be an important factor in hedonic food intake and impaired satiety." (PMID 33574742, 2020). "Furthermore, several drugs including insulin, metformin, and incretin mimetics have shown to improve insulin resistance and mitochondrial functions in vitro and are currently under evaluation for their beneficial effects in neurodegenerative diseases and aging process in humans." (PMID 32733190, 2020). "In addition, the ITT data indicated that piperine could enhance insulin sensitivity and improve insulin resistance in MSG obese mice." (PMID 33028294, 2020). "Moreover, 12-week of CaMKIV injection in obese mice could improve high-fat diet-induced hepatic insulin resistance, further indicating CaMKIV plays an important role in whole-body glucose metabolism and hepatic insulin signaling." (PMID 32660483, 2020). "Additionally, recurrent increases in glucose and insulin could participate in the development of insulin resistance in the brain, as has been observed for a high-GI diet in peripheral tissues." (PMID 33003562, 2020). "In animal models, high dietary selenium intake could upregulate the expression of key factors related to gluconeogenesis and lipogenesis, suppress expression of insulin signaling-related protein, and subsequently induce dyslipidemia, hyperinsulinemia, and insulin resistance." (PMID 32377302, 2020).
Insulin resistance (continued). "To evaluate whether we established a T2D model in high-fat diet (HFD) plus streptozotocin (STZ)-treated mice, we monitored body weight weekly, blood glucose concentration, insulin, and determined the homeostasis model assessment of insulin-resistance (HOMA-IR) index at 2 and 4 months post challenge." (PMID 32194998, 2020). "Thus, insulin resistance can be seen as a protective mechanism for preventing excess activation of glucose transport from the blood despite chronically elevated insulin levels, for maintaining glucose homeostasis in vivo and for mitigating metabolic and oxidative stress due to excess glucose influx." (PMID 32819363, 2020). "Furthermore, omentin increases insulin-induced glucose reuptake and participates in the regulation of insulin sensitivity and, therefore, may exert a protective action against the worsening of insulin resistance." (PMID 32121175, 2020). "While the regulation of insulin responses and development of the pathophysiology of insulin resistance due to overexpression of TNFα and other pro-inflammatory cytokines is well documented, the functional links and interactions that mediate insulin resistance are complex and largely unexplored." (PMID 33257747, 2020). "Furthermore, administration with trilobatin for 4 weeks significantly improved insulin resistance by decreasing fasting blood glucose and insulin in serum, enhancing the phosphorylation of IRS1 and AKT, and recovering the expression and translocation of GLUT4 in ob/ob mice." (PMID 33062046, 2020). "A pilot crossover trial reported that MedDiet for 6 weeks significantly reduced hepatic steatosis (−39%) compared to subjects that undertook a low fat-high carbohydrate diet (−7%), and it also improved insulin sensitivity even without weight loss in individuals with insulin resistance and NAFLD." (PMID 33348700, 2020). "Therefore, to assess whether the upregulation of miR-378b induces insulin resistance in EtOH-fed mice, we injected miR-378b into EtOH-fed mice and assessed the phosphorylation of various insulin signaling intermediates." (PMID 32508647, 2020). "Finally, we have identified a strong positive correlation between adipose cavin-2 downregulation and the HOMA-IR (homeostasis model assessment of insulin resistance) of obese diabetic patient highlighting the importance of functional plasma membrane caveolae in insulin signaling." (PMID 33324235, 2020). "However, a high gluconeogenic enzyme content in human renal biopsies from T2D was reported which could be interpreted as an impairment of insulin action on kidneys, maybe a kidney-specific insulin resistance." (PMID 32377524, 2020). "At the same time, in obesity there is a reduced production of adiponectin, the key insulin-sensitizing adipokine, that regulates glucose and lipid metabolism, activates the energy sensor AMPK and protects against inflammation by inhibiting NF-κB activity and obesity-linked insulin resistance." (PMID 33143088, 2020). "With both targets of insulin sensitivity demonstrating increased expression, it can be concluded that female offspring of dams whole-body irradiated with 1000 mGy are more likely to be insulin resistant or develop insulin resistance in later life compared to the Sham-irradiated group." (PMID 32315370, 2020). "Furthermore, pancreatic fat accumulation induced insulin resistance and impaired insulin secretion." (PMID 33182622, 2020). "Furthermore, the increased total and saturated fat intakes in low carbohydrate- high protein and fat dietary patterns may increase fasting insulin concentrations and could adversely affect glucose metabolism and insulin resistance." (PMID 33042230, 2020). "Therefore, we confirmed that hyperinsulinemia induced insulin resistance in vitro in both 3T3-L1 and SGBS, and it was associated with decreased levels of IR, explaining at least in part the cause of the impairment of downstream insulin signalling." (PMID 32718202, 2020).
Insulin resistance (continued). "Future investigations are undertaken to address the question that whether nutritional mediators stimulate different molecular mechanisms of insulin signalling or endogenous glucose production is responsible for insulin resistance and these paradoxical effects for devising treatments." (PMID 32670384, 2020). "For example, HFD mice have insulin resistance and exhibit hyperinsulinemia with a high level of circulating insulin, a well‐known myoblast proliferation and differentiation enhancer, which may boost SC function and thus compensate HFD‐caused SC harm in vivo, at least in a temporary manner." (PMID 32776502, 2020). "Impaired glucose metabolism, such as type 2 diabetes and insulin resistance, may lead to impaired neuronal insulin signaling, neuroinflammation, oxidative stress, resulting in amyloid-β accumulation, tau hyper-phosphorylation and subsequent cognitive decline and Alzheimer's disease." (PMID 33202379, 2020). "Hence, there is no general insulin resistance but selective impairment of insulin signaling which causes less glucose uptake from the blood and reduced activation of endothelial NO synthase (eNOS)." (PMID 32819363, 2020). "Also, insulin derangements were shown to modify the relationship between adiposity and mortality, as body fat showed a protective effect on survival only in HD patients with insulin resistance." (PMID 33216775, 2020). "Owing to the established link between inflammation and insulin resistance, it is suggested that the insulin-sensitizing effect observed in this study could be a reflection of the potent anti-inflammatory activity of the preparation used due to the presence of phosphatidylserine." (PMID 30796508, 2020). "However, the definite mechanism remains unknown, and it has been controversial whether the main factor of glucose intolerance is impaired insulin secretion or increased insulin resistance." (PMID 33324347, 2020). "Increased HbA1c levels without associated obesity or signs of insulin resistance in the depressed patients could be due to inadequate insulin supply." (PMID 33261587, 2020). "Thus, it can be concluded that the worst effect on insulin resistance and insulin sensitivity in type 2 diabetic patients with end-stage renal disease and kidney failure may be secondary to the strongest effects of inflammation." (PMID 33442388, 2020). "Similarly, another study showed that treatment of patients with T2DM with RSV (1 g/day for 45 days) reduced fasting plasma glucose, plasma insulin concentration and HbA1c, while decreasing homeostasis model of assessment of insulin resistance (HOMA-IR) and HOMA-β index." (PMID 32230718, 2020). "Furthermore, in vivo and in vitro studies have shown how PDE5 inhibition may ameliorate insulin resistance in diabetic mice and sensitize skeletal muscle cells, adipocytes, and endothelial cells to insulin action, thus improving insulin resistance." (PMID 32774364, 2020). "Thus, decreased expression of ABCG1, ABCA1, and ACSL3 could impair insulin secretion and lead to insulin resistance." (PMID 32612641, 2020). "Thus, both mitochondrial disorders and insulin resistance are closely related, because the oxidative stress produced in mitochondria interferes with the translocation of insulin-dependent GLUT4 transporters by accelerating the development of insulin resistance." (PMID 32121669, 2020). "The increase in insulin may also be as a result of insulin resistance which is also supported by the observed significant increase in TNF-α (TNF-α induces insulin resistance by inhibiting insulin signal transduction) and leptin levels (females only) in sugar fed rats compared to honey fed ones." (PMID 32153977, 2020). "Additionally, another study suggested that infliximab treatment in RA and AS patients may improve insulin sensitivity in patients with high insulin resistance." (PMID 32905192, 2020).